FGF4 (fibroblast growth factor 4)
Description:
Plays an important role in the regulation of embryonic development, cell proliferation, and cell differentiation. Required for normal limb and cardiac valve development during embryogenesis. May play a role in embryonic molar tooth bud development via inducing the expression of MSX1, MSX2 and MSX1-mediated expression of SDC1 in dental mesenchyme cells (By similarity).
Synonyms: FGF-4; HST; HST-1; HSTF-1; HBGF-4; HSTF1; K-FGF; KFGF; SRTD22
Tractability: Small molecule: it belongs to a druggable protein family. Antibody: UniProt places it where antibodies can reach, with high confidence; its Gene Ontology location is reachable by antibodies, with high confidence; UniProt predicts a signal peptide or a membrane-spanning region.
Target class: Secreted protein
Gene: Protein-coding gene on chromosome 11 (69,771,022 to 69,775,341, reverse strand). Ensembl gene ENSG00000075388.
Subcellular location: Secreted
Pathways (Reactome):
Signal Transduction: Downstream signaling of activated FGFR1; FGFR1c ligand binding and activation; FGFR2c ligand binding and activation; FGFR3c ligand binding and activation; FGFR4 ligand binding and activation; FGFRL1 modulation of FGFR1 signaling; FRS-mediated FGFR1 signaling; FRS-mediated FGFR2 signaling; FRS-mediated FGFR3 signaling; FRS-mediated FGFR4 signaling; Negative regulation of FGFR1 signaling; Negative regulation of FGFR2 signaling; Negative regulation of FGFR3 signaling; Negative regulation of FGFR4 signaling; PI-3K cascade:FGFR1; PI-3K cascade:FGFR2; PI-3K cascade:FGFR3; PI-3K cascade:FGFR4; PI3K Cascade; PI5P, PP2A and IER3 Regulate PI3K/AKT Signaling; PIP3 activates AKT signaling; Phospholipase C-mediated cascade: FGFR1; Phospholipase C-mediated cascade; FGFR2; Phospholipase C-mediated cascade; FGFR3; Phospholipase C-mediated cascade; FGFR4; RAF/MAP kinase cascade; SHC-mediated cascade:FGFR1; SHC-mediated cascade:FGFR2; SHC-mediated cascade:FGFR3; SHC-mediated cascade:FGFR4
Disease: Activated point mutants of FGFR2; Constitutive Signaling by Aberrant PI3K in Cancer; Signaling by FGFR1 in disease; Signaling by FGFR2 in disease; Signaling by FGFR3 in disease; Signaling by activated point mutants of FGFR1; Signaling by activated point mutants of FGFR3
Developmental Biology: Developmental Lineage of Multipotent Pancreatic Progenitor Cells; Specification of the neural plate border
Gene Ontology:
Molecular function: fibroblast growth factor receptor binding; growth factor activity
Biological process: chondroblast differentiation; fibroblast growth factor receptor signaling pathway; mesenchymal cell proliferation; positive regulation of cell population proliferation; positive regulation of ERK1 and ERK2 cascade; regulation of endothelial cell chemotaxis to fibroblast growth factor; cell-cell signaling; neurogenesis; positive regulation of MAPK cascade; regulation of cell migration; signal transduction
Cellular component: cytoplasm; extracellular region
Genetic constraint (gnomAD): Loss-of-function variants: 9 observed, 11.21 expected, observed/expected ratio (o/e) 0.8, 90% interval 0.48 to 1.4. The synonymous counts are far from expectation, so gnomAD's model fits this gene poorly and the ratio says little. Missense variants: 286 observed, 223.48 expected, observed/expected ratio (o/e) 1.28, 90% interval 1.16 to 1.41. Synonymous variants: 164 observed, 111.66 expected, observed/expected ratio (o/e) 1.47, 90% interval 1.29 to 1.67.
Homologues: Orthologues: chimpanzee FGF4 (99% identical), macaque FGF4 (99% identical), dog FGF4 (93% identical), pig FGF4 (92% identical), guinea pig FGF4 (90% identical), mouse Fgf4 (81% identical), rat Fgf4 (81% identical), rabbit FGF4 (66% identical), tropical clawed frog fgf4 (61% identical), zebrafish fgf4 (58% identical). Paralogues in human: FGF6 (50% identical), FGF5 (36% identical), FGF20 (33% identical), FGF9 (30% identical), FGF16 (29% identical), FGF13 (29% identical), FGF11 (28% identical), FGF22 (28% identical), FGF7 (27% identical), FGF14 (27% identical), FGF10 (26% identical), FGF21 (26% identical), and 9 more.
Diseases named in the same sentence as FGF4 in open-access papers:
FGF4 is named in the same sentence as 99 diseases in open-access papers, as found by Europe PMC text mining. Sharing a sentence is not in itself a finding about the gene and the disease. The quoted sentences say what the papers report.
breast carcinoma (23 papers, 1996 to 2024). "However, overexpression of FGF4 is reported to be associated with aggravation of tumorigenesis and invasion in many cancers, such as hepatocellular carcinoma, lung adenocarcinoma, urinary bladder cancer, ovarian cancer, and breast cancer." (PMID 39766329, 2024). "By contrast, the FGF4 gene is amplified in breast cancer together with FGF3 and FGF15/19 as they are all part of the locus on human chromosome 11q13 that is frequently amplified in several tumours." (PMID 35193394, 2022). "FGF4 signalling regulates breast cancer cell migration and invasion, whereas FGF5 seems to have a specific role in the formation of bone metastasis as shown by its overexpression in metastatic samples compared with normal breast." (PMID 35193394, 2022). "FGF4 promotes resistance to lapatinib in HER2-positive breast cancer cell lines through FGFR1 signalling, and FGF5 by inducing FGFR2 activation, which in turns transactivates HER2 and promotes resistance." (PMID 35193394, 2022). "(A) A random phage display peptide library displaying CX7C inserts (C, cysteine; X any seven residues) was used in vivo to select peptides homing to the microenvironment of EF43.fgf4-derived mammary tumors." (PMID 34060472, 2021). "We selected the EF43.fgf4 syngeneic mouse mammary tumor as a model of a highly aggressive TNBC where features of the microenvironment such as angiogenesis and inflammatory infiltrating cells (TAMs) are biologically important for tumor progression." (PMID 34359704, 2021). "Mice cohorts with size-matched EF43.fgf4 mammary tumors received a single systemic iv administration of targeted CSSTRESAC-AAVP-HSVtk (5 × 1010 TU) or control fd-AAVP-HSVtk." (PMID 34060472, 2021). "(C) Binding of CSSTRESAC-phage to EF43.fgf4 tumor cells and non-malignant stromal cell subpopulations isolated from mCherry-expressing EF43.fgf4-derived mammary tumors." (PMID 34060472, 2021). "(A) FACS analysis of total TAM isolated from EF43.fgf4-derived mammary tumors shows high levels of PDIA3 expression in a subpopulation of F4/80+CD11b+IL10highIL12low TAM." (PMID 34060472, 2021). "We isolated CD11b+F4/80+ TAM from EF43.fgf4 mammary tumors, established them in culture (>99% purity by FACS), and tested cytokine production as a surrogate for immunoregulatory responses upon treatment." (PMID 34060472, 2021). "For instance, miR-511 was described to suppress breast cancer cell proliferation and invasion through targeting FGF4." (PMID 33298078, 2020). "The SNP rs614367 is located in an intergenic region with multiple flanking genes, including CCND1, MYEOV, ORAOV1, FGF19, FGF4 and FGF3, all of which are potential breast cancer susceptibility genes." (PMID 30247654, 2019). "Previously, we described FGF-1- or FGF-4-transfected MCF-7 breast carcinoma cells which are tumorigenic and metastatic in untreated or tamoxifen-treated ovariectomised nude mice." (PMID 8624263, 1996). "EF43.fgf4 breast cancer tumors are known to have an immune infiltrate rich in macrophages." (PMID 37835464, 2023). "Targeted therapy delays growth of EF43.fgf4-derived mammary tumors." (PMID 34060472, 2021). "Prolonged estrogen deprivation in breast cancer cells can lead to upregulation of FGFR1 together with FGF3, FGF4, and FGF19 due to co-amplification of the FGFR gene and genes located in the 11q13 region." (PMID 38255923, 2024). "In a Phase 1/2a study of patients with breast carcinoma harboring an amplification of FGFR1, FGF3, FGF4, or FGF19, lucitanib resulted in a disease control rate (DCR) of 100%; 50% (6/12) of patients achieved PR and 50% (6/12) of patients had SD." (PMID 38380359, 2024). "This chromosomal region is amplified simultaneously with the 11q12–14 region, which contains other oncogenes with a role in breast cancer progression, like CCND1, FGF3, FGF4 and FGF19." (PMID 35193394, 2022).
breast carcinoma (continued). "The human FGF19 gene is amplified in breast cancer together with FGF3 and FGF4, and this correlates with worse prognosis in invasive ductal breast carcinomas, particularly in older patients with lymph node metastasis and negative ER status." (PMID 35193394, 2022). "CNAs in CCND1, FGF3, FGF4, and FGF19, which are all located in the q-arm of chromosome 11 were more likely to be detected from patients with HR+/HER2+ and HR+/HER2− breast cancer (P < 0.001)." (PMID 32695676, 2020). "The region contains CCND1 and other potential oncogenes such as FGF3, FGF4 and MYEOV and there is good evidence that this region is relevant to breast cancer." (PMID 28095868, 2017). "Results of our study showed that stimulation of PR(+) breast cancer cell lines with various FGFs decreased level of PR with the highest impact being observed for FGF1, FGF4, FGF7." (PMID 27852068, 2016). "By contrast, only 31.26% of the promoters of coding genes were aberrantly methylated in breast cancer, some of which were in known disease-related genes, such as HOXB2, FGF4 and TTK." (PMID 25739977, 2015). "Patient samples from this study were previously used to identify a four-marker panel including PITX2, BMP4, FGF4, and C20orf55 which enabled outcome prediction in lymph node-positive, HER-2-negative breast cancer patients treated with anthracycline-based chemotherapy." (PMID 20515469, 2010). "Other studies show no expression of FGF3 and FGF4 in human breast cancers but expression of all other FGFs in at least a small proportion of breast cancers." (PMID 11953856, 2002). "Similar to human breast cancers known to be highly infiltrated by macrophages, the macrophage population (CD11b+F4/80+) constituted a large portion of the non-malignant cellular component of EF43.fgf4-derived mammary tumors, followed by a lesser population of B lymphocytes (CD45R+)." (PMID 34060472, 2021).
chondrodysplasia (11 papers, 2011 to 2025). "Insertions of FGF4 retrogenes in different chromosomal locations were shown to cause chondrodysplasia and/or chondrodystrophy in at least 19 different dog breeds." (PMID 36553621, 2022). "Examples of such variants include the brachycephaly associated SMOC2 and BMP3 variants and chondrodysplasia-associated FGF4 retrogenes on chromosomes 12 and 18, and there are likely more, yet undiscovered variants." (PMID 33599851, 2021). "The causes for both chondrodystrophy and chondrodysplasia were identified as two separate fibroblast growth factor 4 (FGF4) retrogenes on chromosome 12 (12-FGF4RG) and chromosome 18 (18-FGF4RG), respectively." (PMID 31181696, 2019). "Among these, a retrocopy of fibroblast growth factor 4 (FGF4) shows a strong association with a chondrodysplasia phenotype (characterized by short limbs) and is a major genetic factor underlying both this morphology and a high prevalence of intervertebral disc disease (IVDD) in certain dog breeds." (PMID 41473691, 2025). "However, we believe that this variant is more likely a replication of a previous association between the nearby FGF4 retrotransposon and chondrodysplasia across breeds." (PMID 31263560, 2019). "Interestingly, the expression of a newly originated retrogene fibroblast growth factor 4 (fgf4) is strongly associated with chondrodysplasia, a short‐legged phenotype that defined at least 19 dog breeds which include dachshund, corgi, and basset hound." (PMID 31641464, 2019). "Notably, a 590 kb region of low Si overlapping the FGF4 retrogene on chromosome 18 associated with chondrodysplasia in Dachshunds." (PMID 22022279, 2011). "An insertion of an FGF4 retrogene on chromosome 18 produces the chondrodysplasia phenotype without significantly increasing the risk of disc hernias." (PMID 36553621, 2022). "Images received from the owner confirmed that he did exhibit disproportionate dwarfism resembling the more typical breed-defining chondrodysplasia variant in the FGF4 gene, despite testing negative for this mutation." (PMID 29708978, 2018). "The SD2 variant, and the mild phenotype associated with it (short legs with normal body length and width), represents a compelling putative explanation for short-leggedness in the Sussex Spaniel–a breed not reported to carry the common breed-defining chondrodysplasia variant in the FGF4 gene." (PMID 29708978, 2018). "Notably, only a subset of the increased-fear/aggression haplotype under selection contains the FGF4 retrogene insertion that causes chondrodysplasia in some breeds but not in others." (PMID 27503363, 2016). "According to a recent study investigating the effects of FGF4 retrogenes on the conformation, chondrodysplasia itself has no impact on chest height or width at least in Alpine Dachsbracke and Schweizer Niederlaufhund, suggesting that other, yet unknown genes affect the growth of the chest." (PMID 36733429, 2022).
intervertebral disc disease (11 papers, 2016 to 2025). "An additional FGF4 retrogene insertion on CFA12 was also more recently associated with an increased risk for intervertebral disc disease." (PMID 38397188, 2024). "An FGF4 retrocopy on chr18 is associated with disproportionate dwarfism, while an FGF4 retrocopy on chr12 is associated with both disproportionate dwarfism and intervertebral disc disease (IVDD)." (PMID 32717834, 2020). "A genome-wide association study of skeletal dysfunction and intervertebral disc disease in Nova Scotia duck tolling retrievers (NSDTRs) uncovered a different FGF4 retrogene in chromosome 12 as a causative element of these diseases." (PMID 32106563, 2020). "Additionally, chondrodystrophic dog breeds are at increased risk of developing intervertebral disc disease, although recent research has shown that a FGF4-retrogene on CFA12 is of greater importance in intervertebral disc disease in dogs than the one on CFA18." (PMID 33372642, 2020). "However, in dogs with both FGF4 retrogenes, the contribution of 18-FGF4RG to disc degeneration and thus IVDD is unknown." (PMID 31181696, 2019).
dwarfism (5 papers, 2010 to 2024). "Comparatively, activating mutations of the FGFR3, one of the receptors for FGF4, are responsible for some of the most common causes of disproportionate dwarfism in humans including achondroplasia." (PMID 32793650, 2020). "Two different FGF4 retrogenes have been associated with dwarfism across dog breeds." (PMID 35205370, 2022). "In humans, the most common genetic cause of achondroplasia (dwarfism) is caused by a substitution mutation in the FGF receptor FGFR3, one of the receptors for FGF4." (PMID 38397188, 2024). "Two FGF4 retrogenes (FGF4L1 on chromosome 18 and FGF4L2 on chromosome 12) have been identified to cause dwarfism across many dog breeds." (PMID 35205370, 2022). "Interestingly, the most common form of human dwarfism is caused by reoccurring activating mutations in the FGFR3 gene, which is one of the receptors for FGF4." (PMID 35205370, 2022). "Two separate retrogenes, derived from the parental FGF4 gene on CFA18, have been described in dogs resulting in various degrees of skeletal dysplasia and disproportionate dwarfism." (PMID 32793650, 2020).
lymphoma (5 papers, 2014 to 2021). A malignant (clonal) proliferation of B- lymphocytes or T- lymphocytes which involves the lymph nodes, bone marrow and/or extranodal sites. "For instance, in the Eu-myc + lymphoma mouse model, the secretion of fibroblast growth factor-4 (FGF4) by lymphoma cells and its binding to the cognate receptor FGFR1 on endothelial cells prompts Notch ligand Jagged1 (Jag1) expression by these cells." (PMID 34395425, 2021). "In B cell lymphoma, Jag1 induced the expression of FGF4 which in turn activated Notch2 in lymphoma cells." (PMID 32028262, 2020). "Interestingly, B-cell lymphomas have been reported to produce FGF4, which upregulates Jag1 on adjacent endothelial cells, that in turn induces Notch2 regulation of Hey1 in the lymphoma cells." (PMID 25309874, 2014). "Similarly, in the context of lymphoma, a specific population of lymphoma cells was shown to up-regulate endothelial Jagged1, through the secretion of FGF4, which in turn up-regulates Notch2 and consequently Hey1 in the tumor cells promoting growth, aggressiveness and resistance to chemotherapy." (PMID 26213336, 2015).
seminoma (5 papers, 2013 to 2022). A radiosensitive malignant germ cell tumor found in the testis (especially undescended), and extragonadal sites (anterior mediastinum and pineal gland). "In a previous study, we demonstrated that TCam-2 cells directly differentiate in vitro into a cell type resembling a mixed non-seminoma, when being cultivated in fibroblast-conditioned medium supplemented with FGF4/heparin." (PMID 27283990, 2016). "Additionally, TCam-2 can be forced to differentiate into a mixed non-seminoma upon cultivation of murine fibroblast conditioned medium supplemented with FGF4." (PMID 27283990, 2016). "In previous studies, we demonstrated that the seminoma cell line TCam-2 differentiates into a mixed non-seminoma, when being cultivated in murine embryonic fibroblast conditioned medium supplemented with FGF4 /Heparin or in a combination of FGF4 /TGF-B1 /EGF, which mimics a somatic microenvironment." (PMID 26226633, 2015). "TGF-β1, together with EGF and FGF4, synergistically contribute to differentiation of seminoma cells into the mixed non-seminoma-like cell type." (PMID 31842336, 2019).
B cell lymphoma (4 papers, 2020 to 2023). "Studies in B cell lymphoma show that tumors stimulate the neighboring endothelium via fibroblast growth factor 4 (FGF4) to upregulate the Notch ligand Jagged 1 (JAG1)." (PMID 37887354, 2023).